CD44 (CD44 molecule (IN blood group))
Diseases named in the same sentence as CD44 in open-access papers (continued):
Sharing a sentence is not in itself a finding about the gene and the disease.
cancer (continued). "This suggests that CAF-derived HA interacts with the nearest M2-TAMs and cancer cells through CD44, promoting the upregulation of PD-L1 together with PD-1–expressing T cells to create a protumorigenic immunosuppressive TME in steatotic liver." (PMID 39946200, 2025). "The simultaneous expression of all three analyzed putative cancer stem cell markers (CD133 within CD44/CD166 double-positive population) was found to range from 0.5% to 53.6% (median 2.0%)." (PMID 41303421, 2025). "Here, we report for the first time that LNPs modified with a CD44-specificpeptide achieved enhanced targetability and antitumor efficacy towardhuman CD44+ cancers after codelivering YAP/TAZ-siRNA." (PMID 40176316, 2025). "Receptors for HA overexpressed in subpopulations of cancer cells, and one of them, CD44, is recognized as a molecular marker for cancer stem cells." (PMID 39851489, 2025). "Many studies have demonstrated NP systems conjugated with hyaluronic acid, a CD44 native ligand, as a promising approach to the targeted delivery of therapeutic agents to cancer stem cells, which are often responsible for MDR." (PMID 40867257, 2025). "CD44 expression is correlated with redox balance and chemoresistance and is a promising target for enhancing the prognosis and treatment of various cancers." (PMID 40864800, 2025). "For instance, a study has shown that the macrophage-derived soluble glycoprotein NMB (GPNMB) induces cancer stemness and metastasis via CD44 and IL-33." (PMID 41174767, 2025). "Recent studies have highlighted the key role of CD81 in promoting cancer stemness and metastasis by interacting with CD44, a cell surface adhesion receptor which is highly expressed in many cancers." (PMID 40411659, 2025). "CD6 interactions with its ligands—CD166/ALCAM, CD318, and CD44—are important in the pathogenesis of various autoimmune diseases and cancer." (PMID 39996744, 2025). "CD44 isoforms were detectable in the serum of 6 of 8 cancer patients and in 12 of 16 ascitic fluid samples." (PMID 41440277, 2025). "CD44 positive cells display enhanced self-renewal, tumorigenicity, and chemoresistance, making this marker suitable for cancer stem cell enrichment." (PMID 40866457, 2025). "Complementing this pathway, the stemness factor SOX2 maintains cancer cell plasticity and therapy resistance through regulation of stem cell markers including CD44 and OCT4." (PMID 40508204, 2025). "Stem-like CD8+T cells (Tsl, CD44+TCF1+) have recently been identified as crucial immunocytes for sustaining long-term cancer immunity and responding to immunotherapy, persisting in TdLNs throughout disease progression 14-15." (PMID 41208878, 2025). "PDAC cancer stem cell markers including CD44, MET, CD133, FUT4, ACVR1, mTOR, and KLF4 were positively related to IARS2 expression." (PMID 40092487, 2025). "CD44 is a well-characterized transmembrane glycoprotein that is used as a common biomarker for cancer stem cells in many cancers." (PMID 41463154, 2025). "For instance, in bone metastases, HA retention on the surface of cancer cells is possibly mediated by CD44." (PMID 40176023, 2025). "CD44 is significantly elevated in a range of cancers, including those affecting the breast, lungs, ovaries, brain, and liver." (PMID 41233827, 2025). "CD44 is linked to stem cell characteristics, whereas CD24 expression is associated with cancer cell differentiation." (PMID 39932626, 2025). "As a cancer stem cell marker, CD44 has been found to play a crucial role in promoting cancer cell metastasis." (PMID 40409554, 2025). "CD44, a multifunctional cell surface glycoprotein, has garnered attention for its involvement in various aspects of cancer biology." (PMID 40114966, 2025). "NANOG is a key regulator of stem cell properties, and CD44 is involved in cell adhesion, movement, and signaling, both playing roles in cancer stem cells (CSCs) in PDAC." (PMID 40429900, 2025).
cancer (continued). "They found that the prepared theranostic LPs-loaded anti-CD44 antibody showed an enhanced effect on cancer cells compared to curcumin-loaded and CUR/CD-loaded LPs." (PMID 40806663, 2025). "TME cells directly contact the surrounding matrix via their membrane receptors, like CD44 and integrins, coordinating the complex signaling networks that drive cancer." (PMID 40542654, 2025). "The α-SMA+ CAFs can promote the generation and proliferation of CD44+CD24− breast cancer stem cells by secreting CXCL12 that activates CXCR4 on cancer cells." (PMID 39780187, 2025). "All analyzed OSCC samples demonstrated positive expression for the putative cancer stem cell markers: CD44, CD133, and CD166." (PMID 41303421, 2025). "The detector-enabled visual detection of CD44 expression on cancer cells for cancer drug resistance monitoring works in this manner." (PMID 40292706, 2025). "It has been reported that Met can affect stemness properties as it reduces the expression levels of CD44, a well‐known stemness‐related marker, in cancer cells." (PMID 40387464, 2025). "Moderate hypoxia provides favorable oxygen conditions for cancer stem cell proliferation, and it also reduces CD44 expression, as observed in the present study, decreasing the highly migratory and invasive activities of GSCs." (PMID 40002787, 2025). "CD44+ cells were separated from the heterogenous cancer cell cultures using Fluorescence-Activated Cell Sorting (FACS)." (PMID 39941011, 2025). "Research on various cancer cell lines has identified a positive feedback loop between CD44 and ZEB1, which represses ESRP1 gene activity, thereby promoting CD44s splicing and reinforcing EMT." (PMID 40538061, 2025). "CD44 has been identified in multiple cancers, including breast, prostate, colorectal, and pancreatic." (PMID 40791212, 2025). "This paracrine MIF–CD74/CD44 interaction is a well-recognized mechanism of immunosuppression in the TME: MIF is often overexpressed in cancers and can drive macrophages toward an “M2” immunosuppressive, pro-tumoral phenotype." (PMID 40740766, 2025). "We narrowed the list to cell adhesion molecules (GO:0007155), such as CD44 and N-cadherin, which are key factors in tumorigenesis, chemoresistance, and cancer stem cell plasticity." (PMID 40518514, 2025). "The current method of X-aptamers offers several advantages over traditional antibody and aptamer technologies, particularly in targeting CD44-positive cells, including cancer stem cells." (PMID 40001633, 2025). "On the other hand, CD44 is commonly regarded as a marker of cancer stem cells (CSCs), which possess increased plasticity and self-renewal capabilities that are believed to drive disease relapse and therapy resistance." (PMID 40707771, 2025). "Together, these findings support a mechanistic model in which extracellular HA regulates glycosylation metabolism and cancer cell migration through CD44, mediated by the Wnt signaling pathway." (PMID 41461315, 2025). "In conclusion, we developed a conditionally replicative adenovirus vector, CRAd-synNotch, and a recombinant adenovirus vector, ADX730, containing a synNotch receptor gene that inhibits CD44 signaling and hypoxia-induced response in cancer cells." (PMID 40011711, 2025). "Targeting CD44 offers a promising avenue for overcoming therapeutic resistance and improving the outcomes of refractory cancers." (PMID 40259468, 2025). "While CD44 is a well-established marker of cancer stem cell features, its direct targeting remains challenging due to the diversity of CD44 isoforms and their context-dependent roles." (PMID 40430044, 2025). "In particular, CD44 shows promise as a potential biomarker of progression and resistance to therapy in various cancers." (PMID 40141159, 2025). "The resulting receptor–ligand stabilizations mirror prior experimental studies on HA-mediated active targeting to CD44-overexpressing cancer cells." (PMID 40573202, 2025).
cancer (continued). "The expression of CD44 variants and TFF2 expansion are key markers of human gastric metaplasia and are associated with cancer stem cell properties and progression risk." (PMID 40673273, 2025). "Flow cytometry was then utilized to isolate CD133+CD44+ cells, indicative of CSC properties, and CD133-CD44- cells, representative of typical cancer cell characteristics, from HCT116 cells." (PMID 40901481, 2025). "In particular, Cur@(Zn–Adenine)@HA demonstrated excellent biocompatibility and strong specificity for targeting CD44 protein on cancer cells." (PMID 40733206, 2025). "Analysis of TCGA data reported that HNSCC has the second-highest CD44 expression among all cancer types." (PMID 41465166, 2025). "Despite higher presence of immune cells, these cancers demonstrated activation of immunosuppressive pathways involving CD44 and galectin-3 that are frequently seen in ICI-resistant cancers." (PMID 41374966, 2025). "This dual-phase survival pattern highlights the complex and context-dependent role of CD44 in cancer progression and therapy resistance." (PMID 40534867, 2025). "In pathological conditions, particularly in cancers, CD44 plays a crucial role in promoting the invasion, migration, and metastasis of cancer cells." (PMID 41009438, 2025). "CD44 plays a pivotal role in cancer biology, and is a key regulator of CSC characteristics and metabolic pathways." (PMID 40259468, 2025). "When HA binds to CD44, it activates pathways that encourage cancer cell growth, making CD44 a valuable target for anti-cancer strategies." (PMID 41233827, 2025). "CSC transcription factors (such as SOX2, OCT4, KLF4 and CD44) are important marker of cancer and normal stem cells." (PMID 39611488, 2025). "CD44 plays a crucial function in activating many signaling pathways that trigger the epithelial-mesenchymal transition, a vital mechanism that allows cancer cells to invade and spread." (PMID 38544254, 2024). "Although accumulating evidence suggests that CD44 plays a key role in the clinicopathological features of numerous cancers, there are relatively few clinical studies designed to evaluate the efficacy of CD44‐targeted therapies in cancer treatment." (PMID 38783892, 2024). "Other interesting mechanisms of targeting CD44 in cancer include recombinant human proteoglycan 4 (rhPRG4)." (PMID 38612911, 2024). "Different studies proved that the derivatization of nanoparticle systems with the CD44 native ligand (HA) is a valuable approach to selectively target cancer cells, thus enhancing the uptake of a loaded therapeutic agent." (PMID 39408889, 2024). "More precisely, MIF downregulated the interaction between cancer-associated fibroblasts and immune cells including B cells, DCs, myeloid derived suppressor cells, monocytes, NK cells, and T cells via the CD74/CD44 and CXCR2/CXCR4 signaling pathways." (PMID 38638429, 2024). "CD44, a marker for many cancer stem cells, is also thought to play a role in the creation of cancer stem cells through cell fusion." (PMID 39184916, 2024). "Although exposure to RIS decreased the growth rate and the size of the spheroid compared to the vehicle-treated control, levels of CD44+CD133+ cancer stemness tended to be improved by the chemical stressors." (PMID 39518936, 2024). "CD44, a hyaluronic acid transmembrane glycoprotein overexpressed by CSCs, is known for regulating the adhesion, survival, migration and motility of cancer cells." (PMID 39768151, 2024). "This study aims to compare the differences in radiation sensitivity of A549 and CD44+A549 stem-like cells to X-rays and carbon ion radiation (C-ions), and to find a target that can kill cancer stem-like cells (CSCs) of non-small cell lung cancer (NSCLC)." (PMID 39457544, 2024). "Expression results also showed that castration-rebound VCaP-NURR1 tumors expressed enhanced levels of phenotypic markers of EMT (reduced E-cadherin and increased vimentin levels) and cancer stemness (increased CD44 and Oct4a, and decreased CD24 levels)." (PMID 38531859, 2024).
cancer (continued). "To correlate the CD44 expression to iron uptake, we used an antibody to block CD44 and examined the iron uptake in cancer cells following prolactin treatment." (PMID 39201626, 2024). "Pre-clinical studies have shown that CD44 knockdown diminishes the ability of cancer cells to enter glycolysis and enhanced the efficacy of chemotherapeutic drugs." (PMID 38539529, 2024). "The results showed that the CD44 levels in metastatic tissues were higher than that in non-cancer tissues." (PMID 38385088, 2024). "When Fn infects cells, it leads to changes in CD44 expression and triggers cancer stem cell-like behavior, making these cells capable of forming tumors and migrating." (PMID 39981299, 2024). "Immune checkpoint analysis revealed that basically all the checkpoints were upregulated in the low-risk group except for CD44, TNFSF4/9, and CD276 (marker of cancer stem cell)." (PMID 38341588, 2024). "Secondly, immune or cancer cells expressing CD44 interacts with other cell membrane-expressed or anchored HA to mediate cell adhesion." (PMID 38736891, 2024). "The crosstalk between the JAK/STAT pathway and other pathways, such as the formation of complexes between STAT3/SMAD3 and STAT3/CD44, contributes to the generation of cancer stem cells." (PMID 38553760, 2024). "This signal forms a complex with the receptor CD44 on cancer cell surfaces, activating the PDE3B signalling pathway through the integrin enzyme pathway, consequently leading to the resistance of cancer cells to chemotherapy drugs." (PMID 38982317, 2024). "Our fabricated A6 peptide functionalized nanoparticles with CD44 and Hsp90 targets are expected to possess a broad anti-cancer spectrum both in hematological malignancies and solid tumors, which are rarely reported in nanomedicines." (PMID 38649957, 2024). "The resulting sensor exhibits an excellent antifouling capability and biocompatibility, making it highly effective to identify the target protein CD44 and detect CD44-positive cancer cells." (PMID 39451710, 2024). "All told, CD44 protein provides a number of opportunities to better monitor and therapeutically target cancer and deserves increased resources to further clarify this potential." (PMID 38539529, 2024). "CD44, a transmembrane glycoprotein, is typically overexpressed on cancer cells, exhibiting a strong affinity for HA, leading to cancer progression." (PMID 38543448, 2024). "Studies were also reported that α6β4 integrin mediated SRC/β-catenin signaling enhances cancer stemness properties by upregulating CD44 and EGFR47." (PMID 38839865, 2024). "The objective of this study is to develop a packaged biosensor capable of identifying the CD44 cancer biomarker in a dynamic environment, aimed towards clinical use." (PMID 38544254, 2024). "Next, the cBioPortal database was used to analyze the overall genome alternations of CD44 in 10,967 samples from 32 types of cancer in TCGA." (PMID 38590654, 2024). "The oral spheroids cultured in the microfluidic system expressed the cancer stemness marker (CD44+) and maintained high viability for 5 days." (PMID 38890730, 2024). "CD44 protein is known to be involved in drug resistance and to act as a cancer stem cell (CSC) biomarker." (PMID 38391955, 2024). "Cellular growth against 4T1 (CD44) is an attractive molecular candidate for targeted drug delivery in cancer treatment." (PMID 38799466, 2024). "These lines of evidence suggest a link between EGFR expression and the progression of CD44+-mediated cancer stem cells." (PMID 38699644, 2024). "In fact, it is in cancer cells that the alternatively spliced CD44 protein isoforms have been found to be expressed at their highest levels." (PMID 38539529, 2024). "PTBP1 increases alternative splicing events of CD44 to produce CD44 v8-10, which promotes cancer cell invasion." (PMID 38785973, 2024).
cancer (continued). "The main novelty of the work is an in-depth study of the capability of an in-house fabricated optical fiber biosensor for in situ detection of a cancer biomarker (CD44 protein) by conducting several types of experiments." (PMID 38544254, 2024). "The addition of γ-secretase inhibitors, namely, MK-0752 and RO4929097, to chemo/radiotherapy gave indications of reducing cancer stem cell populations (CD44+, CD24−/low, ALDHhigh, and CD133+ cells), encouraging their assessment in haematological malignancies." (PMID 38612718, 2024). "EV CD44 has also been proposed to be instrumental in dictating the characteristic organotropism of cancer metastases." (PMID 38542421, 2024). "Several strategies have been applied to inhibit CD44 for cancer therapy, including HA nanoparticles, small-molecule inhibitors, and anti-CD44 mAbs." (PMID 38736891, 2024). "GO enrichment analysis was conducted on 100 genes screened by GEPIA2 with the highest correlation with CD44 in pan-cancer." (PMID 38590654, 2024). "In this scenario, our analysis proposes CD44 and other co-receptors as attractive targets for cancer therapy." (PMID 38761292, 2024). "When these EVs from FSS were introduced to MCF-7 cancer cells, the recipient cells had a significant increase in their stem-like gene expression and CD44+/CD24− cancer stem cell-like subpopulation." (PMID 39062471, 2024). "Its interactions with its main receptor, CD44, play a significant role in various aspects of tumorigenesis and cancer progression." (PMID 38672650, 2024). "It is well-known that CD44 is a cancer stem cell marker and epithelial–mesenchymal transition factor in breast and other cancers." (PMID 39273689, 2024). "This scoping review, following PRISMA-ScR guidelines, systematically identified and evaluated clinical studies on the impact of CD44 expression on chemotherapy treatment outcomes across various cancer types." (PMID 38542115, 2024). "The (CD44+/CD24-) SKOV3-derived “twin” cells lack expression of CD24, often associated with cancer stemness." (PMID 39592661, 2024). "The integral membrane glycoprotein CD44 is considered one of the cancer stem cell (CSC) markers for HNSCC and is widely used to assess the relevance of organoids or immortalized cell lines derived from these tumors." (PMID 38540309, 2024). "Hyaluronic acid, for example, has been used to increase the binding affinity of nanoparticles selectively for the surface of cancer cells and was found to mediate the targeting recognition of CD44 over-expressing cancer cells." (PMID 38675078, 2024). "The group showed that a distinct population of CD44+ and CD44− cancer cells was identifiable from resected primary HNSCC tumors." (PMID 39335624, 2024). "Overall, the complex relationship between CD44 and MMPs expression provides us with more ideas for selecting different targets in cancer therapeutic strategies." (PMID 38783892, 2024). "RIS partially enhanced CD44+CD133+ cancer stemness, which was remarkably upregulated by CTGF deficiency, indicating that CTGF is a crucial regulator of cancer cell stemness." (PMID 39518936, 2024). "Recently, CD44 has been used to identify different cancer stem cells (CSCs), such as lung cancer, breast cancer, colon cancer, blood system cancer and others." (PMID 38706601, 2024). "Second, since CD44 binds a sugar moiety called hyaluronic acid, chemotherapy agents can be packaged with hyaluronic acid so that they preferentially bind cancer cells with high levels of CD44 on their surface, resulting in a greater efficacy in treatment." (PMID 38539529, 2024). "Remarkably, the expression of CD44 is highly upregulated in various cancers and this molecule is recognized as a molecular marker of cancer stem cells (CSCs)." (PMID 38542421, 2024). "CD166, CD318, and CD44 are widely expressed by both differentiated cancer cells and cancer stem-like cells, and the level of their expression generally correlates with poor prognosis and increased metastatic potential." (PMID 39840036, 2024).